IGF2 (insulin like growth factor 2)
Diseases named in the same sentence as IGF2 in open-access papers (continued):
Sharing a sentence is not in itself a finding about the gene and the disease.
breast carcinoma (continued). "As a biomarker predictive of response to the MEK inhibitor AZD6244 in breast cancer, we identified ENST00000346192, one of the longest isoforms of the insulin-like growth factor 2 mRNA-binding protein 2 (IGF2BP2), which codes a protein with 556 amino acids." (PMID 29066719, 2017). "In MCF-7 human breast cancer cells, IR and DDR1 co-immunoprecipitated and co-localized after insulin or IGF-2 stimulation." (PMID 28591735, 2017). "Insulin-like growth factor (IGF) binding protein 3 (IGFBP3) is a major carrier of IGF1 and IGF2 in circulation and IGFBP3 levels are reduced in breast cancer patients, giving rise to higher free IGF1 levels and poor prognosis." (PMID 24534923, 2014). "Here we show that hypermethylation of the DMR2 of IGF2 is specifically observed in ERBB2 positive breast cancers providing a new potential mechanistic link between IGF1R expression and ERBB2 status via IGF2 methylation status." (PMID 20338046, 2010). "Even though it is known that the circulating IGF2 concentration is much higher than that of IGF1, there is limited evidence on its mitogenic activity in relation to breast cancer and disease, thus implications of IGF2 on breast cancer risk are inconclusive." (PMID 20302654, 2010). "FGF13-AS1 has been found to play a predominantly oncogenic role in breast cancer, reducing the glycolytic and stemness properties of breast cancer cells by inhibiting MYC expression through binding to insulin-like growth factor 2 mRNA-binding proteins (IGF2BPs)." (PMID 37204526, 2023). "Breast cancer patients with disease and illness development situation may be affected by the IGF-1 and IGF-2 expression." (PMID 35845730, 2022). "This study aims to explore the efficacy of ultrasound combined with the molybdenum target detection mode in clinical diagnosis and evaluation of the development of breast cancer and to perform IGF-1 and IGF-2 detection for patients with different degrees of disease." (PMID 35845730, 2022). "The study investigates the diagnostic efficacy of ultrasound combined with the molybdenum target mode in breast cancer staging and the relationship between blood flow parameters and the expression of insulin-like growth factor 1 (IGF-1) and factor 2 (IGF-2) and prognosis." (PMID 35845730, 2022). "The proliferation and survival of HER2-positive breast cancer cells are inhibited by negative feedback inhibition of IGF2/IGF-1R/IRS1." (PMID 36210846, 2022). "In summary, we discover a FOXO3a-miRNA negative feedback inhibition loop to control the IGF2/IGF-1R/IRS1 signaling in HER2-positive breast cancer cells sensitive to Herceptin." (PMID 33976188, 2021). "The data showed that higher expression of IGF2 and/or lower expression of miR-98 were significantly correlated with poor overall survival (OS), recurrence free survival (RFS) and distant metastasis-free survival (DMFS) in HER2-positive breast cancer." (PMID 34837929, 2021). "Collectively, we demonstrate that the IGF2/IGF-1R/IRS1 signaling is aberrantly activated in Herceptin-resistant breast cancer via disruption of the FOXO3a-miRNA negative feedback inhibition." (PMID 33976188, 2021). "The level of IGF2 expression was lower in breast cancer than normal tissue, regardless of any subtype." (PMID 34837929, 2021). "We discover a negative feedback inhibition of IGF2/IGF-1R/IRS1 signaling in HER2-positive breast cancer cells to maintain basic cell survival and proliferation." (PMID 33976188, 2021). "Moreover, we detect significantly increased IGF2 in blood and IRS1 in the tumors of breast cancer patients with poor response to Herceptin-containing regimens." (PMID 33976188, 2021). "In spite of these advances, there is currently no consensus regarding the methylation status of the IGF2 gene, and its relationship to the levels of IGF2 protein expressed in normal breast or in breast cancer tissues." (PMID 33216823, 2020).
breast carcinoma (continued). "In one large follow-up study on breast cancer in postmenopausal women, serum levels of IGF-2, but not IGF-1, were positively associated with oestrogen receptor-positive breast cancer risk." (PMID 33114046, 2020). "Moreover, IGF-2 is closely related to the proliferation of bovine retinal pigment epithelial cells and MCF-7 human breast cancer cells." (PMID 32399056, 2020). "By inhibiting IGF2 signaling using silencing or picropodophyllin (PPP), we could block the proliferation‐increasing effect of pericytes on breast cancer cells." (PMID 32534480, 2020). "This analysis has revealed a number of intact transcripts that are massively upregulated by recurrent geneUIB fusions, including IGF2 in colorectal, ETV1 in prostate, IGF2BP3 in thyroid, and ANO3, LIPG, FUT5, and RSG9 in breast cancers (ordered by the expression fold change within a tumor type)." (PMID 32631391, 2020). "Similar to what we observe at the primary site, metastasis-associated macrophages and fibroblasts express high levels of Igf-1 and Igf-2, whereas disseminated breast cancer cells do not express these ligands." (PMID 29367764, 2018). "In a panel of breast cancer cells, DDR1 knockdown by specific siRNAs markedly inhibited IR downstream signaling as well as proliferation, migration and colony formation in response to insulin and IGF-2." (PMID 28591735, 2017). "In order to evaluate whether the DDR1 and IR co-localize in breast cancer cells, MCF-7 cells were plated onto coverslips, serum-starved for 24h and stimulated with either insulin or IGF-2 at a dose of 10nM for 5 and 20 min." (PMID 28591735, 2017). "Moreover, H19 has the potential to produce 91H RNA, which regulates insulin like growth factor 2 (IGF2) expression and is over-expressed in breast cancer cells." (PMID 27027436, 2016). "Then, we investigated whether HMGA1P7 functions as ceRNA through, or partially through H19, IGF2 and HMGA1 in breast cancer human cells." (PMID 27874091, 2016). "Further analysis of genes associated with breast cancer, including ABCB1, BRCA1, GSTP1, IGF2, and TERT, showed a high CM fraction in cancer but non-CM in normal cell lines." (PMID 26659027, 2015). "High expression of insulin-like growth factor 1 receptor (IGF1R) and its two ligands, insulin-like growth factor 1 (IGF1) and insulin-like growth factor 2 (IGF2) have been demonstrated in OS, as well as many other cancers including rhabdomyosarcoma, breast cancer, prostate cancer, and colon cancer." (PMID 25170759, 2014). "IGF-1 and IGF-2 signal through specific cell surface tyrosine kinase receptors, IGF-1 receptor (IGF-1R) and insulin receptor isoform A (IR-A)), that are highly expressed on human ER expressing breast cancer cells." (PMID 24171117, 2013). "IGF-2 is involved in the development of breast cancer, and its expression rate is not the same in different tissues." (PMID 22662119, 2012). "Loss of imprinting of IGF2 resulting in increased expression of IGF-2 is a common genetic alteration in human malignancies and aberrant methylation of IGF2/H19 locus has been detected in multiple human cancers including breast cancer." (PMID 23148692, 2012). "In breast cancer (BC), lncRNA FGF13-AS1 can regulate RNA binding proteins and insulin-like growth factor 2 mRNA binding proteins (IGF2BPs) to shorten the half-life of c-Myc (Myc) mRNA." (PMID 39030557, 2024). "To date, there is no study showing whether an IGF2 neutralization Ab may abrogate Herceptin resistance in breast cancer." (PMID 33976188, 2021). "In addition, pericytes secreted insulin‐like growth factor 2 (IGF2), which had a very significant pro‐proliferative effect on mammary carcinoma, but not on melanoma cells." (PMID 32534480, 2020). "Finally, we show that expression of HMGA1P7 significantly correlates with H19 and IGF2 levels in human breast cancer, suggesting the upregulation of HMGA1P7 may increase H19 and IGF2 expression by a ceRNA mechanism then contributing to cancer progression." (PMID 27874091, 2016).
breast carcinoma (continued). "Pericytes produce insulin-like growth factor 2 (IGF2), which supports the proliferation of mammary carcinoma but not other cancers." (PMID 39766062, 2024). "The fact that IR is not enriched in the CSC population, and that IGF-1 and IGF-2 are more effective regulators of CSC function than insulin, supports a dominant role for the IGF-1R in regulating breast cancer stemness." (PMID 36556357, 2022). "In order to confirm this, expression levels of IGF2 protein levels in breast cancer cells with or without CD44+Fbs or CD44−Fbs were examined by Western blotting and IGF2 indeed expressed much higher in breast cancer cells cocultured with CD44+Fbs than with CD44−Fbs." (PMID 28523716, 2017). "Analysis of The Cancer Genome Atlas database showed that, unlike primary PIK3CA‐wild‐type and HER‐2+ breast carcinomas, PIK3CA‐mutant tumors display increased expression of AXIN2, HGF, STAT3, IGF‐1, and IGF‐2 mRNA and activation of AKT, IGF1‐MTOR, and WNT canonical signaling pathways." (PMID 28296140, 2017). "Only IGF2 DMR0 (rho = 0.65, p<0.001) and IGF2 DMR2 (rho = 0.50, p = 0.026) displayed a significant correlation between tissue and blood in women with invasive breast cancer but not in women free of breast cancer." (PMID 23409079, 2013).
Hypoglycemia (135 papers, 2006 to 2026). A decreased concentration of glucose in the blood. "IGF2 was pinpointed as the cause of hypoglycemia occurring in a very small subset of SFTs (Doege–Potter syndrome)." (PMID 40875449, 2025). "Elevated circulating IGF-2 can cause clinically significant hypoglycemia through an affinity for IR-A." (PMID 40270996, 2025). "GISTs are rare mesenchymal tumors, typically arising in the stomach or small intestine, and can, in exceptional cases, secrete IGF-2 and cause hypoglycemia via the NICTH pathway." (PMID 41333493, 2025). "The hypoglycaemia is caused by the overexpression of IGF-2; this results in an increase of circulating precursors of the IGF-2 protein." (PMID 39931615, 2025). "As the tumor size and associated IGF-2 excess increased further, overt symptomatic hypoglycemia then developed." (PMID 41179270, 2025). "Exuberant levels of IGF-2 secreted by the tumor tend to cause hypoglycemia that mimics hypoglycemia caused by insulin-secreting PanNETs." (PMID 40522948, 2025). "Yet, aberrant secretion of IGF-2 causing paraneoplastic hypoglycemia is uncommon in the setting of ACC." (PMID 41209155, 2025). "This case demonstrates a rare IGF-2–secreting ACC causing clinically significant hypoglycemia with positive immunostaining for IGF-2 in addition to biochemical hyperandrogenism resulting in endometrial hyperplasia and postmenopausal bleeding." (PMID 40270996, 2025). "ERT with an IGF2-tagged GAA analog caused dose-dependent hypoglycemia shortly after drug administration in patients with Pompe disease." (PMID 41023195, 2025). "NICTH is a paraneoplastic syndrome that manifests through excess IGF‐2‐led insulin receptor activation, causing hypoglycaemia." (PMID 38411039, 2024). "The treatment of IGF‐2‐mediated hypoglycaemia can be divided into two phases: acute management, which can be similar to hypoglycaemia of other causes, and definitive treatment by focusing on reduction in tumour function." (PMID 38411039, 2024). "Nonislet cell tumor hypoglycemia (NICTH) is an uncommon cause of hypoglycemia due to a relative surplus of insulin-like growth factor 2 (IGF-2) or its precursor molecule." (PMID 39372824, 2024). "Recurrent hypoglycemia has often been described in SFTs in previous reports and is caused by high levels of insulin-like growth factor 2 (IGF2) produced by the tumor." (PMID 38982409, 2024). "Excess IGF-2 causes hypoglycemia by activating the insulin receptor-B isoform resulting in an insulin-like effect." (PMID 39372824, 2024). "The most effective approach for treating NICTH involves using glucocorticoids, which suppress the production of IGF-2, thereby addressing the hypoglycemia caused by "big" IGF-2." (PMID 39219869, 2024). "Once IGF-2 excess and recurrent hypoglycemia are established, localisation of the underlying tumour is warranted if not already identified." (PMID 38432069, 2024). "IGF-2-mediated hypoglycemia is an exceedingly rare and probably under-recognised cause of hypoglycemia in the setting of epithelial or mesenchymal tumours." (PMID 38432069, 2024). "The hypoglycemia risk of exogenous IGF2 is primarily influenced by two factors: dose and route of administration." (PMID 36971212, 2023). "The insulin-like effects of IGF-2 not only ameliorated his long-standing type 2 diabetes mellitus, but also caused spontaneous fasting hypoglycemia." (PMID 37908275, 2023). "Meanwhile, the binary complex and free IGF-2 pass through capillary membranes relatively easily and bind to insulin receptors, subsequently causing hypoglycemia." (PMID 36034453, 2022). "This indicates that, in the mouse, therapeutic levels of IGF2.GAA were several orders of magnitude below the levels that can cause hypoglycemia." (PMID 36284764, 2022). "We inferred that preoperative hypoglycemia was most likely caused by the high expression of IGF-2 in the phyllodes tumor." (PMID 33841338, 2021).
Hypoglycemia (continued). "We report a rare case of hypoglycemia caused by a relapsing pelvic solitary fibrous tumor associated with Big-IGF-2 production." (PMID 33633907, 2021). "And then combining with relevant literature and perioperative blood glucose changes and the postoperative immunohistochemical staining, we inferred that the hypoglycemia symptoms were most likely caused by the high expression of IGF-2 in the phyllodes tumor." (PMID 33841338, 2021). "Abundant serum big IGF-2 was detected by western immunoblot analysis, indicating it to be the cause of the hypoglycemia." (PMID 32993631, 2020). "Herein, we report a case of malignant SFT associated with a hypoglycemia attack, and we discuss the associations among IGF2, IGF1R, and IGF2R in SFT based on analyses of the tumor in this case." (PMID 30168002, 2018). "Definitive management of hypoglycemia associated with paraneoplastic production of IGF-2 consists of resection of the tumor responsible for IGF-2 production." (PMID 24934576, 2014). "Review of recent reported cases of NICTH identified widespread anatomic locations and varied pathologic diagnoses of tumors associated with paraneoplastic production of IGF-2 causing hypoglycemia." (PMID 24934576, 2014). "These tumours are known to cause hypoglycemia via secretion of IGF-2 that leads to stimulation of insulin receptors." (PMID 24741994, 2014). "On our review of literature, we identified 22 published reports of NICTH with elevated IGF-2 levels causing hypoglycemia." (PMID 24934576, 2014). "This suggests that, during gene therapy, the level of expression of IGF2 moieties may be several fold lower compared to the previously observed concentration range associated with hypoglycemia." (PMID 41023195, 2025). "The most accurate hypothesis is that NITCH is caused by tumor overexpression of IGF-2, both mature IGF-2 and incompletely processed IGF-2, which has potent insulin-like activity causing hypoglycemia." (PMID 39867043, 2024). "Salivary MRCAs commonly contain pleomorphic adenoma gene 1 oncogene rearrangements which are associated with increased IGF-2 production and may predispose patients to hypoglycemia." (PMID 39372824, 2024). "Additionally, we emphasize that malignant SFT commonly causes severe hypoglycemia due to the production of IGF2." (PMID 38982409, 2024). "In addition, higher IGF2 level increases peripheral glucose utilization, diminishes liver's glucose production, and causes hypoglycemia." (PMID 37143466, 2023). "In addition, it has been demonstrated that SFT has the potential to produce big IGF2 and cause hypoglycemia." (PMID 37469410, 2023). "In brief, associations of increased serum levels of IGF2 with hypoglycaemia as well as of total and free IGF2 (defined as bound or unbound fractions of IGF2 with IGFBPs, respectively) with obesity accompanying Type 2 Diabetes mellitus (T2DM) have been suggested." (PMID 36982475, 2023). "This confirmed that the core factor of hypoglycemia is caused by the high molecular weight IGF-2." (PMID 33841338, 2021). "The symptoms of preoperative hypoglycemia in this case may have been caused by IGF-2 in tumor cells." (PMID 33841338, 2021). "Our case demonstrates that severe hypoglycemia may be the first presenting symptom for SRS-like cases associated with IGF2 hypomethylation." (PMID 33922271, 2021). "NICTH is rare in GIST of the stomach; however, the large GIST could produce big-IGF2 and subsequently cause severe hypoglycemia, requiring prompt evaluation and complete tumor resection." (PMID 32393233, 2020). "Nevertheless, other tumors unrelated to β cell may cause hypoinsulinemic hypoglycemia by producing insulin growth factor-2 (IGF2) or its precursor named as big-IGF2." (PMID 27134683, 2016). "However, plasma concentrations of IGF-1 and IGF-2 can be 1000 times greater than insulin in NICTH allowing them to cause hypoglycemia." (PMID 24934576, 2014). "Hypoglycemia is caused by the insulin-like growth factor 2, which is secreted by the tumors." (PMID 21958732, 2011).